IL15RA (interleukin 15 receptor subunit alpha)
Diseases named in the same sentence as IL15RA in open-access papers (continued):
Sharing a sentence is not in itself a finding about the gene and the disease.
tumor (continued). "The anti-tumor effects of IL-15 have been documented following systemic administration of IL-15 in complex with soluble IL-15Rα, as well as engineering tumor cells to produce IL-15 alone in the local tumor microenvironment." (PMID 24312353, 2013). "Continuing studies are warranted to investigate anti-tumor and anti-virus immune responses elicited by oHSV production of mIL-15/IL-15Rα in vivo." (PMID 24312353, 2013). "The construction of J100D, demonstrated to produce soluble, bioactive mIL-15/IL-15Rα complex enables the investigation of combinatorial anti-tumor approaches using oHSV and mIL-15/IL-15Rα in multiple cancer models." (PMID 24312353, 2013). "When mice bearing the NK-sensitive syngeneic tumor B16 were treated, the presence of IL-15Rα-IgG1-Fc increased the anti-tumor activity of IL-15." (PMID 19319200, 2009). "Antitumor effects have been demonstrated for fusion proteins composed of antibodies targeting different tumor-associated antigens (e.g., CEA, EDB, EDA, GD2, EGFR, FAP) and many cytokines of the common gamma chain receptor family (e.g., IL-2, IL-15, IL-15/IL15Rα, IL-21, IL-7)." (PMID 40370435, 2025). "Additionally, IL15 has the potential to bind with IL15Rα on cancer cells, promoting their proliferation and migration independently of IL15Rβ/γc, thus counteracting its immunological anti‐tumor efficacy." (PMID 39625860, 2025). "In mouse study, Pembrolizumab-IL-15Rα-IL-15 expressed acceptable tumor growth inhibition." (PMID 39808627, 2025). "The specific receptor of IL-15 (IL-15Rα) is secreted primarily by NK, T, and B cells.Binding of IL-15R to IL-15Rα produces the IL-15R/IL-15Rα complex, which binds to the IL-2Rβγ (IL-15Rβγ) expressed by effector cells (NK, T, and B cells), and further activates them to kill tumor cells." (PMID 40469178, 2025). "After binding to IL-15Rα, IL-15 is trans-presented to the IL-2R/IL-15Rβ and -γ heterodimer expressed on effector T, B, and NK cells, thereby enhancing survival and maturation of the effector cells for killing tumor cells." (PMID 38368374, 2024). "Furthermore, the 4T1 tumor model was also established to compare the therapeutic outcomes of heterodimeric IL-15 (IL-15:IL-15Rα) and the MIST platform." (PMID 37875481, 2023). "Nanovesicles derived through extrusion overexpressing the IL-15/IL-15Rα (IL-15/IL-15Rα-NVs) complex boosted the proliferation, activation, and survival of tumor-infiltrated T-cells via the trans presentation of IL-15 to T-cells and the eliminated tumor." (PMID 37345176, 2023). "IL-15Rα expression was also measured in tumor lysates using ELISA." (PMID 37465665, 2023). "The in vivo results demonstrated the enhanced anti-tumor potential of NK-92-CAR-19-IL-15/IL-15Rα cells, which may further improve the clinical use of NK-CAR cells." (PMID 37818365, 2023). "Furthermore, aerobic exercise promotes anti-tumor immunity and reduces tumor growth in pancreatic cancer through the accumulation of tumor-infiltrating IL15Rα+ CD8 T cells." (PMID 37208766, 2023). "IL-15/IL-15Rα reverted the tumor growth effect and mediated T-cell driven tumor spheroid killing." (PMID 37923822, 2023). "Next we evaluated whether the transgenic IL-15/IL-15Rα expression was sufficient to induce tumor cell killing." (PMID 37923822, 2023). "Additionally, overexpression of soluble IL-15 (sIL15) or membrane-bound IL-15 (mbIL15; IL-15Rα/IL15 complex) to generate IL-15-armored immune cells has demonstrated enhanced anti-tumor effects and cell persistence." (PMID 35806311, 2022). "In addition, H89 induces overexpression of genes involved in anti-tumor immune response (such as IL-15RA), and its depletion counteracts the anti-tumor effect of H89." (PMID 37305350, 2022). "It was demonstrated that soluble IL-15Rα could act as an enhancer of inflammatory cytokines, such as IL-6, TNFα, and IL-17, which can, in turn, lead to tumor evasion." (PMID 35806311, 2022).
tumor (continued). "Other molecules that are being studied include NKTR-255, a novel polyethylene glycol-conjugate of rhIL-15, and NIZ985, a recombinant heterodimer of IL-15/IL15Rα, both of which have shown promising anti-tumor efficacy in a preclinical and phase I clinical trial, respectively." (PMID 36231109, 2022). "Therefore, the stability of IL-15/IL-15Rα complex is essential for IL-15 to perform tumor immune function." (PMID 34386015, 2021). "Similarly, a vaccinia virus expressing the chemokine CXCL11 or IL15Rα enhanced the anti-tumor activity of CAR T cells in solid tumors." (PMID 33801359, 2021). "Although it is well established that IL-15 or IL-15/IL-15Rα complex can be a potent stimulator of T cytotoxic and NK cells, high levels of IL-15 or the complex can actually result in reduced proliferation, exhaustion, and reduced anti-tumor activity." (PMID 33096755, 2020). "Importantly, a significant antitumor activity including long-term complete tumor regression has been shown in animals treated with intratumoral delivery of IL-15/IL-15Rα co-expressing DNA." (PMID 33628206, 2020). "Since it had been demonstrated that the CD40 agonist also increases the expression of IL‐15Rα on DCs, we hypothesised that combining both agents may result in enhanced immune activation and increased anti‐tumor effects." (PMID 32821382, 2020). "Since it has been demonstrated that CD40 agonists also increase the expression of IL‐15Rα on DCs, we hypothesised that combining both agents might result in enhanced immune activation and increased anti‐tumor effects." (PMID 32821382, 2020). "However, the synergistic effect of rMVA-CD40L and anti-TRP-1 TAA-specific mAb was lost in IL15rα−/− tumor-bearing mice, in contrast to the effects observed in WT counterparts treated with the combination." (PMID 31695037, 2019). "Moreover, anti-CTLA-4 combined with IL-15/IL-15Rα enhances the NK cell tumor infiltration, improving the tumor growth control in xenograft murine models of solid tumors." (PMID 32038612, 2019). "Indeed, peripheral blood NK cell frequencies were drastically reduced in IL15rα−/− tumor bearers, whereas transgene-specific and vector-specific CD8+ T cells were expanded upon vaccination (respectively)." (PMID 31695037, 2019). "Since mRNA electroporation is broadly accepted to introduce tumor antigens into DC, in situ cotransfection with immune-stimulatory molecules like IL-15 and IL-15Rα mRNA can be easily performed in one electroporation step, avoiding the need of time- and cost-consuming manipulations." (PMID 28785596, 2017). "In our study it remains unclear, and therefore requires further investigation, whether the expression of IL15 and/or IL15Rα at the tumor site has any relevant/conditional effect in tumor growth inhibition." (PMID 26822794, 2016). "The superior tumor-cell killing effect of IL-15/IL-15Rα EP DC/NK-cell cocultures leveled out to the cytotoxic level of IL-15 EP DC/NK-cell cocultures using transwells, indicating that a contact-dependent IL-15 transpresentation mechanism is involved in the superior killing effect (p < 0.001)." (PMID 26675759, 2015). "In vivo experiments in RAG1-/- mice showed that subcutaneous B16-F10 tumors treated with vMyx-IL15Rα-tdTr exhibited attenuated tumor growth and a significant survival benefit for the treated group compared to the PBS control and the control viruses (vMyx-IL15-tdTr and vMyx-tdTr)." (PMID 25329832, 2014). "Finally, another group of constructs (anti-GD2RLI, 2B8T2M, IL15 trike) exploits the targeting mediated by a specific antibody for a tumor-associated antigen (TSA) to direct the activity of effector cells activated by the IL15/IL15Rα sushi domain complex to tumor cells." (PMID 39858511, 2025). "Moreover, IL15RA is expressed in various cells, including malignant tumor cells." (PMID 39396119, 2024).
tumor (continued). "For example, the IL15_IL15RA interaction produces a two-sided effect, with IL-15 promoting the proliferation and maintaining the survival of certain T cells as well as consistently promoting anti-tumor responses and being crucial for controlling tumor growth and metastasis in vivo." (PMID 37818360, 2023). "However, IL-15 must form the IL-15/IL-15Rα complex in order to exert its tumor immune function." (PMID 34386015, 2021). "ACTM-838 utilizes the STACT platform to deliver IL-15/IL15Rα and a constitutively active STING to tumor-resident phagocytic antigen-presenting cells." (PMID 41048107, 2025). "Consistent with our hypotheses, ACTM-838, the STACT chassis carrying a plasmid that encodes IL-15/IL-15Rα and a constitutively active form of STING, exhibited a significantly decreased acute systemic proinflammatory cytokine response compared to VNP20009 in tumor-bearing mice upon IV dosing." (PMID 41048107, 2025). "IL-15Rα+ve TAMs lowered CX3CL1 protein levels in tumor cells, inhibiting CD8+ve T cell recruitment via secretion of the IL-15/IL-15Rα complex (IL-15Rc)." (PMID 39858015, 2025). "In conclusion, NKG2D CAR-T cells co-expressing IL-15/IL-15Rα promoted the central memory CAR T cell proliferation and improved the homing and persistence of CAR T cells in vivo, resulting in enhanced anti-tumor and anti-viral effects in treating EBV-PTLD." (PMID 39160631, 2024). "Gene-based delivery of IL-15/IL-15Rα to tumor cells, shows expansion of NK cells, activation of NK cells, CD4+ and CD8+ T cells, and killing of tumor spheroids." (PMID 37923822, 2023). "We showed that genetically delivered IL-15/IL-15Rα acts on NK cells, CD4+ and CD8+ T cells during PBL-mediated tumor cell killing." (PMID 37923822, 2023). "Thus, we propose that the presence of mbIL-15 and secreted IL-15/IL-15Rα complexes could in early tumor stages promote the production of cytotoxic lymphocytes cells (T and NK cells), but promote the accumulation of dysfunctional tumor infiltrated lymphocytes in stage IV." (PMID 37334356, 2023). "Immunization with this IL-15:IL-15Rα cancer vaccine delayed tumor growth in mice by inducing effector memory CD4+ and CD8+ cells and effector NK cells which are tumor-infiltrating." (PMID 34439192, 2021). "Therefore, we share their view on the need of caution and propose that the clinical administration of recombinant IL15 alone could be efficient and sufficient in NK cell-mediated tumor eradication thus avoiding potentially immunostimulatory molecules generated by the combination of IL15Rα with IL15." (PMID 26822794, 2016). "Accordingly, RAG1-/- mice bearing established subcutaneous B16-F10 tumors were injected intratumorally (i.t.)with vMyx-IL15Rα-tdTr, vMyx-tdTr or PBS on days 7 and 10 post tumor cell injection." (PMID 25329832, 2014). "C57BL/6 mice with subcutaneous B16-F10 tumors were injected intratumorally with vMyx-IL15Rα-tdTr, vMyx-tdTr or PBS on days 7 and 10 post tumor cell injection." (PMID 25329832, 2014). "Analysis of T cell subsets in this response revealed that most tumor infiltrating T cells were CD8+, although CD4+ cells were also elevated in vMyx-IL15Rα-tdTr treated tumors compared to controls." (PMID 25329832, 2014). "In the case of CAR-19 NK-92 cells, armouring with IL-15/IL-15Rα led to enhanced in vitro proliferation (in the absence of IL-2) and in vivo tumour control compared to soluble IL-15." (PMID 41463563, 2025). "Localized delivery of eSTING and IL-15/IL-15Rα via ACTM-838 exhibits effective synergistic activity to engage both innate and adaptive immunity in the tumor and generate a durable T-cell mediated systemic anti-tumor immune response." (PMID 41048107, 2025). "Nonetheless, final tumor weights between plant-produced Pembrolizumab-IL-15Rα-IL-15 and Keytruda groups were not significantly different (P = 0.31)." (PMID 39808627, 2025).
tumor (continued). "Based on the effects of NKG2D CAR and IL-15/IL-15Rα on virus-infected cells and tumor cells, as well as the NKG2DL expressions on B-LCL cells of EBV-PTLD mouse models, we propose IL-15/IL-15Rα co-expressing NKG2D CAR-T for the treatment of EBV PTLD - an approach that has not been reported thus far." (PMID 39160631, 2024). "The failure of the IL-15/IL-15Rα complex in the treatment of cancer has not been considered to date in light of its actions on tumor cells." (PMID 38637902, 2024). "Furthermore, exercise promotes immune mobilization and accumulation of tumor-infiltrating IL-15Rα+ CD8 T cells, which reduces tumor growth effectively." (PMID 38622609, 2024). "The co-expressed IL-15/IL-15Rα complex could prolong the proliferation and survival of NKG2D CAR-T cells, resulting in superior anti-tumor and antiviral effects in EBV-PTLD models." (PMID 39160631, 2024). "Also, the Pavlakis group showed that multiple peri-tumoral injections of hetIL-15, the heterodimeric IL-15/IL-15Rα in EO771 TNBC tumors resulted in significant tumor regression, increased host survival and prevention or elimination of metastasis." (PMID 39559362, 2024). "For example, IL15RA, whose expression decreased upon LINC00173 depletion, is a neutrophil attractant, indicating that LINC00173 may act as a tumor suppressor by promoting anticancer immunity." (PMID 38069335, 2023). "Similarly, the administration of the IL-15/IL-15Rα immune complex induces activation and expansion of both NK and CD8 T cells, which become highly functional with enhanced anti-tumor responses." (PMID 36231109, 2022). "In our study, we found that IL-15 combined with IL-15Ra reduced adverse events significantly during CAR-T therapy that had the potential ability to prolong the survival rate of tumor-treated mice with the health liver and lower GVHD score, indicating a novel function of IL-15Ra." (PMID 36167591, 2022). "We tested here, using a replicating oncolytic virus (OV) that expresses IL-15/IL-15Rα (vvDD-IL15/Rα) in vivo, a strategy to enhance recovery of autologous tumor-specific memory CD8+ T cells which could be utilized for ACT." (PMID 33679747, 2021). "At the lower dose of 0.3 × 105 cells/mouse which secreted IL-15:IL-15Rα in the range of 10–25 pg/mL, the immunization did not inhibit tumor growth effectively." (PMID 34439192, 2021). "The amount of IL-15 expressed and the presence or absence of IL-15Rα in the treated tumors did not significantly affect the tumor regression and long-term survival." (PMID 33096755, 2020). "We sought to determine if increased local IL-15 expression, with or without the presence of IL-15Rα would result in greater anti-tumor response and protection." (PMID 33096755, 2020). "Importantly, 25% (2/8) of animals obtained complete tumor regression and remained tumor free following GET with plasmid IL-15/IL-15Rα." (PMID 33628206, 2020). "In EE mice lacking IL-15Rα, we failed to observe the modulation of inflammatory genes, and tumor size did not decrease." (PMID 29286001, 2017). "Despite trans-presentation being an important process for adequate CD8+ T cell immunity, NK cells were capable of inhibiting tumor development in the absence of IL15Rα exprseesion in our in vivo model of tumor metastasis." (PMID 26822794, 2016). "So, after treatment with ttIL15 or wtIL15, the accumulated IL15 protein in the tumor environment is limited by the lack of available IL15rα." (PMID 24369443, 2013). "The production of mIL-15/mIL-15Rα from multiple tumor lines, as well as the lack of neurovirulence, renders J100D suitable for investigating the combined effects of oHSV and mIL-15/IL-15Rα in various cancer models." (PMID 24312353, 2013). "Engineering Dex with increased expression of both IL-15Rα and NKG2D ligands could lead to a significant enhancement of anti-tumor responses in vivo." (PMID 19319200, 2009).
tumor (continued). "Remarkably, without IL-15/IL-15Rα, K2-Fc alone had modest impact on most lymphocyte activation markers, besides CD137 on NK cells, and was not able to drive anti-tumor immune responses profoundly." (PMID 37923822, 2023). "Infusing Perforin-/- CD137L/IL-15/IL-15Rα activated NK cells had no impact on GVT, whereas TNF-α-/- CD137L/IL-15/IL-15Rα activated NK cells improved GVT by decreasing peripheral effector cell subsets while preserving tumor-infiltrating lymphocytes." (PMID 34489927, 2021). "In contrast to most in vitro studies involving PBLs, we did not address the anti-tumor functions of NK and T cells individually but evaluated the interplay between CD4+ T cells, CD8+ T cells and NK cells on immune cell activation and tumor lysis upon delivery of IL-15/IL-15Rα and K2-Fc." (PMID 37923822, 2023).